RUNX1 (RUNX family transcription factor 1)
Diseases named in the same sentence as RUNX1 in open-access papers (continued):
Sharing a sentence is not in itself a finding about the gene and the disease.
leukemia (continued). "The 8;21 chromosomal rearrangement disrupts the key hematopoietic RUNX1 transcription factor, and contributes to leukemia through recruitment of co-repressor complexes to RUNX1 target genes, altered subnuclear localization, and deregulation of the myeloid gene regulatory program." (PMID 28611288, 2017). "In addition, Mx1-Cre+; Cbfb+/56M; Runx1+/lz mice show significantly delayed leukemia development as compared to Mx1-Cre+; Cbfb+/56M; Runx1+/+ mice." (PMID 27542261, 2016). "Furthermore, we also identified a strong correlation in ETV6/RUNX1-positive leukemias between NETO1 and its adjacent, bidirectional lncRNA lnc-TIMM21-5 (r = 0.89) as well as between LRP8 and lnc-CPT2-7 (r = 0.70)." (PMID 27650541, 2016). "However, several recent studies found that RUNX1 plays a prosurvival role by supporting leukemia cell proliferation." (PMID 26910834, 2016). "Although Runx1 participation has been widely described in the hematopoietic system and leukemia, during the last years different studies have indicated that this transcription factor could be also involved in other cancer types." (PMID 26735887, 2016). "This confirms the importance of RUNX1 in CBFβ-SMMHC-expressing leukemia cells." (PMID 27542261, 2016). "Interestingly, BCL2 was also shown to be essential for the survival effect of RUNX1 in human MLL fusion leukemia." (PMID 26919255, 2016). "Given the predicted link between these lncRNAs and resistance to vincristine, we examined whether these lncRNAs are able to identify a more aggressive subtype of ETV6/RUNX1-derived leukemia." (PMID 27650541, 2016). "Interestingly, 16 out of 50 lncRNAs overlapped with the ETV6/RUNX1-specific lncRNA signature that was identified in the primary leukemia samples, including 14 up- and 2 down-regulated lncRNA transcripts." (PMID 27650541, 2016). "Interestingly, 13/15 samples showed a gain on 21q22.12 containing RUNX1, a gene involved in translocations in different types of leukemia and generally considered a tumor suppressor in myeloid neoplasms." (PMID 27481518, 2016). "E/Rtg mice were bred with Vav-BCL2 transgenic mice to assess whether the antiapoptotic protein BCL2 would cooperate with ETV6/RUNX1 to initiate leukemia." (PMID 26919255, 2016). "Investigation of the role of RUNX genes in cancer started with the discovery of RUNX1 as an important translocation breakpoint in leukemia, and dysregulation of RUNX-mediated gene expression has also been linked to the development and progression of malignancy." (PMID 25537508, 2015). "Animal models have revealed that RUNX1-related translocations or haploinsufficiency of RUNX1 are necessary but not sufficient for leukemogenesis, which suggests the requirement for additional genetic lesion for the development of leukemia." (PMID 25879624, 2015). "In this context CDK1 inhibition may provide a therapeutic benefit in MLL-rearranged leukemia through its ability to block RUNX1." (PMID 25914884, 2015). "DEK/NUP214 and RUNX1/RUNX1T1 both induced leukemia with a low efficiency and long latency." (PMID 25568664, 2014). "We also found important differences between the two subtypes of leukemic cells, with Leukemia 1 cells overexpressing a number of important leukemia regulators, including Etv6 and Runx1, providing support that these cells are more important for tumor initiation." (PMID 25517911, 2014). "The RUNX1 transcription factor is widely recognised for its tumour suppressor effects in leukaemia." (PMID 24967588, 2014). "Although RUNX1 mutations do not seem to be sufficient to trigger leukemia, many of them are associated with poor outcome." (PMID 23344057, 2013). "The identification of inherited mono-allelic RUNX1 intragenic deletions in familial platelet disorder (FPD), which is associated with a higher risk to develop AML, points to RUNX1 haploinsufficiency, and not only RUNX1 translocations, as a leukemia pre-disposing factor." (PMID 23344057, 2013).
leukemia (continued). "Thus, deregulation of RUNX1-miRNA circuits is expected to be critical not only in the pathogenesis of leukemia, but also of other malignancies." (PMID 23344057, 2013). "Milne and colleagues now show that a protein named RUNX1 cooperates with two different MLL mutations to alter the epigenetic information content of the cell, directly contributing to the poor prognosis of MLL-associated leukemias." (PMID 23352661, 2013). "The centrality of RUNX1 circuits in hematopoiesis is further supported by the dramatic biological effects consequent to RUNX1 perturbation in hematopoietic malignancies (e.g., leukemia)." (PMID 23344057, 2013). "However, RUNX1 overexpression in childhood leukemias has been reported, whereas oncogenic function has been identified in other cancers, such as T cell lymphomas." (PMID 23352661, 2013). "RUNX1 is a regulatory gene in hematopoiesis and plays a key role in the development of leukemias." (PMID 22720055, 2012). "Mice with Runx1 deficient HSCs do not spontaneously develop leukemia, but are sensitized to leukemia caused by experimentally induced secondary mutations." (PMID 22145044, 2011). "Aberrations in the expression of RUNX1 were identified in a significant proportion of leukemias." (PMID 21203558, 2010). "Indeed, previous work has shown that proliferation of the human leukemia cell line ME-1 can be inhibited by compounds that disrupt the interaction between Runx1 and CBFβ." (PMID 20591170, 2010). "Thus, the expression patterns of a number of differentially expressed genes, chosen due to potential functions in leukemia development, were compared to that of RUNX1." (PMID 18671852, 2008). "These regions of UPD seemed to be non-random and may be used to unmask pre-existing recessive mutations in leukemia genes, such as CEBPA, WT1, FLT3 and RUNX1." (PMID 18221515, 2008). "The disruption of the largely unknown biological pathways controlled by RUNX1 is likely to be responsible for the development of leukemia." (PMID 18671852, 2008). "Thus, at this stage leukemia cells had "double-hit" abnormality in RUNX1." (PMID 42283395, 2026). "We also show that RUNX1 and PTBP1 co-localize at the promoters of actively transcribed genes, including key metabolic genes, and that loss of PTBP1 decreases expression of target genes, resulting in impaired glycolysis and cell death, linking RUNX1 to the control of metabolism in leukemia." (PMID 41214140, 2026). "In addition, cells from leukemia 241 carried deletions in Runx1 and Phf6." (PMID 40394211, 2025). "However, chimeric mice expressing CBFβ-SMMHC with deletion of the HABD (CBFβ-SMMHC-ΔHABD) only partially rescued the hematopoiesis phenotype, and unexpectedly accelerated leukemia development caused by CBFβ-SMMHC, challenging the importance of RUNX1 for CBFβ-SMMHC–mediated leukemogenesis." (PMID 40763310, 2025). "Similar pathogenic fusion genes are found in leukemias, such as AML1 (acute myeloid leukemia-1)-ETO (eight twenty-one), PML (promyelocytic leukemia)-RARα (retinoic acid receptor alpha), and ETV6 (ETS variant transcription factor 6)-RUNX1 (RUNX family transcription factor 1)." (PMID 40584293, 2025). "Also, for high-risk populations, especially for pre-HSCT MRD-positive patients, Haplo-HSCT can mediate a more substantial graft-versus-leukemia (GVL) effect than HLA-matched sibling donor transplantation, making it a promising treatment option for AML patients with RUNX1 mutations." (PMID 40558237, 2025). "In support of this hypothesis, the latency of leukemia induced by a viral model of RUNX1::RUNX1T1 9 A was significantly shortened when expressed in both Mga(±) and Mga(−/−) hematopoietic cells, and the resulting leukemic cells displayed a more immature phenotype." (PMID 38454121, 2024).
leukemia (continued). "Collectively, our data highlight MGA as an important regulator of pathways critical for leukemia development, such as MYC activation, cell cycle, and oxidative phosphorylation, and that loss of function mutations identified in patients can functionally cooperate with the RUNX1::RUNX1T1 oncoprotein." (PMID 38454121, 2024). "However, a truncated version of RUNX1::RUNX1T1 was reported to directly induce leukemia in mice." (PMID 38201282, 2023). "Hence, overexpressing RUNX1::RUNX1T1 in human CD34+ as a single genetic element rather models a pre-leukemic phase of AML allowing for the investigation of additional hits to progress to leukemia." (PMID 38201282, 2023). "Furthermore, the TF POU4F1 is known to be overexpressed in RUNX1/RUNX1T1 leukemia." (PMID 36980682, 2023). "To date, there have been no officially approved drugs effective for leukemia with RUNX1 mutations." (PMID 38007419, 2023). "Somatic mutations in RUNX1 are associated with the progression of chronic myelogenous leukemia (CML) to blast crisis, and chromosomal translocations resulting in the generation of fusion genes such as RUNX1-ETO, RUNX1-EVII, etc., are frequently reported in leukemia." (PMID 37903788, 2023). "Therefore, overexpression of wild-type RUNX1 in DS cells (due to an extra copy of the gene) is predicted to decrease, rather than augment, the risk of leukemia." (PMID 37670378, 2023). "This supports the notion that germline RUNX1 mutations are not solely sufficient to develop neoplasia, but favor the acquisition of additional somatic mutations in an inflammatory environment required for the development of overt leukemia." (PMID 35884491, 2022). "Indeed, RUNX1/AML1 was first described as a frequent target of translocations in leukemia." (PMID 34421907, 2021). "Indeed, previous literature on the distribution of cytogenetic abnormalities among ALL patients of varying racial and ethnic groups has suggested that ETV6/RUNX1 leukemia is less common in Hispanics and East Asian populations compared with populations of European ancestry." (PMID 33968846, 2021). "Thus, we speculated that RUNX1 could also have an impact on THP-1/leukemia cell differentiation potential." (PMID 34434964, 2021). "RUNX1 mutant directly enhanced the transcriptional activity of HIF-1α and increased its target gene expression such as ID1 which could be a potential target for future therapy in ASXL1-mutated leukemia." (PMID 31640815, 2019). "Interestingly, expression of a causative fusion protein in acute myeloid leukemia, Runt-related transcription factor 1(Runx1/AML1)-ETO, also caused expansion of hemocyte precursors, supporting the idea that Drosophila hemocytes provide a reasonable model for leukemia mechanisms." (PMID 30558204, 2018). "This indicates that CBFβ-SMMHC has effects on gene expression that are not due to loss of the RUNX1 activity, and that RUNX1 repression-independent activities may be important for leukemia development." (PMID 27542261, 2016). "The discovery of mutations in ANKRD26, RUNX1, and the ETS family transcription factors has led to an increased understanding of the genetic basis of hereditary syndromes involving thrombocytopenia, red cell macrocytosis and leukemia and of the pathways regulated by these genes." (PMID 26102509, 2015). "Likewise, it should also provide an attractive treatment option for RUNX1/ETO-mediated leukemia." (PMID 23865046, 2013). "Furthermore, KLF6 is specifically upregulated by RUNX1-ETO in human leukemia cells." (PMID 24130502, 2013). "The RUNX1 gene is involved in several different and frequently recurring translocations with various partner genes in leukaemia, and point mutations or deletions of this gene are relevant as well in the pathogenesis of different types of MDS and leukaemia subtypes." (PMID 23025896, 2012). "Based on our data, we propose that the interaction between RUNX1 and PTBP1 facilitates expression of metabolic proteins essential for leukemia cell growth and survival." (PMID 41214140, 2026).
leukemia (continued). "Our lab previously showed that HDAC1 is required for active transcription of RUNX1 target genes in a mouse model of CBFβ::SMMHC (CM) driven AML, making leukemia cells particularly sensitive to the HDAC1 inhibitor, entinostat." (PMID 41214140, 2026). "We sorted CM+, GFP+ leukemia cells for KIT and CSF2RB, markers we previously showed distinguish between these two populations in this mouse model, and performed PLA for RUNX1 and PTPB1." (PMID 41214140, 2026). "Five independent mouse CM+ leukemia samples were treated with 1 μM entinostat, an HDAC1 inhibitor, or DMSO for 24 h, nuclear lysates prepared, RUNX1 immunoprecipitated, and the precipitate analyzed by mass spectrometry." (PMID 41214140, 2026). "In this study, we performed proteomic and phosphoproteomic profiling of samples collected at diagnosis and remission from pediatric leukemia patients with one of two subtypes of B-ALL: BCR::ABL1-like (Ph-like) and ETV6::RUNX1." (PMID 40832224, 2025). "Increased binding affinity between transcription factor RUNX1 and its DNA target sequences is a critical mechanism for the fusion gene CBFB-MYH11 to induce leukemia." (PMID 40763310, 2025). "To test this, we knocked down Runx1 in multiple models—c-Kit+ bone marrow progenitors from Srsf2P95H and U2AF1S34F mice, K562 with SRSF2P95H and KO52 leukemia cells that naturally harbor SRSF2P95H—and measured CHK1 inhibitor sensitivity." (PMID 41279606, 2025). "It has been shown by many groups, including ours, that CBFβ-SMMHC sequesters most RUNX1 to the cytoplasm, supporting a dominant-negative model for CBFβ-SMMHC–induced leukemia development." (PMID 40763310, 2025). "Toward this goal, we first identify RUNX1 as a key TF that recruits JMJD1C to chromatin, a mechanism shared by multiple types of leukemia." (PMID 39450904, 2025). "To extend these approaches to pediatric leukemias, we profile samples from patients diagnosed with one of two well-defined subtypes: BCR::ABL1-like and ETV6::RUNX1 B-ALL, which have distinct prognoses, known signaling pathways, and treatment approaches." (PMID 40832224, 2025). "Finally, we show that CBFβ-SMMHC could not induce leukemia in mice with a Runx1-R188Q mutation, which reduces RUNX1 DNA binding but does not affect its interaction with CBFβ-SMMHC or its sequestration to cytoplasm by CBFβ-SMMHC." (PMID 40763310, 2025). "Our recent data suggested that Runx1 is indispensable for Cbfb-MYH11–induced leukemogenesis, functioning cooperatively with CBFβ-SMMHC to regulate critical genes for leukemia initiation." (PMID 40763310, 2025). "Taken together, these data add to our understanding of the molecular profile of Ph-like and ETV6::RUNX1 B-ALL, demonstrating the utility of multi-omic comparison in pediatric leukemia subtype characterization." (PMID 40832224, 2025). "Pathological analysis of the bones (sternum), brain and meninges, liver, and lungs further show that RUNX1::RUNX1T1 9 A expression in Mga(±) and Mga(−/−) HSPCs leads to mice that are more severely infiltrated by leukemia compared to control mice." (PMID 38454121, 2024). "Overall, the AE oncogenic fusion protein, which contains the RHD of RUNX1 and all four NHRs of ETO, drives leukemia development by dysregulating the expression of hematopoietic genes." (PMID 37838757, 2024). "RUNX1 activates the AP-1/GATA2 axis in the bone marrow microenvironment, thereby leading to the aberrant proliferation of leukemia stem cells and the promotion of their immune escape." (PMID 39422621, 2024). "This was confirmed in vivo as Mga(±) and Mga(−/−) HSPCs expressing RUNX1::RUNX1T1 9 A rapidly expanded and developed into leukemias characterized by immature GFP+, cKit+ myeloid progenitor-like cells when transplanted into lethally irradiated recipient mice." (PMID 38454121, 2024).
leukemia (continued). "Most of these are recurrent and class-defining in pAML (for example, KMT2Ar, 20.3%; RUNX1::RUNX1T1, 12.4%), whereas we also found fusions recurrent in other leukemias, such as SET::NUP214 (n = 1) or SFPQ::ZFP36L2 (n = 1)." (PMID 38212634, 2024). "However, these inherited RUNX1 variants are not sufficient to cause leukemia." (PMID 38203823, 2024). "E2A-PBX1 is recruited to gene-binding sites by RUNX1, and RUNX1 is a target gene of E2A-PBX1, which upregulates the expression of RUNX1 and promotes the transformation and proliferation of leukemia cells." (PMID 39129784, 2024). "Most of these are recurrent and class-defining in pAML (e.g., KMT2Ar: 20.2%, RUNX1::RUNX1T1: 12.3%), whereas we also found fusions recurrent in other leukemias, such as SET::NUP21427 (n=1) or SFPQ::ZFP36L228 (n=1)." (PMID 37398194, 2023). "Altogether, several pieces of evidence, including data from 3 different murine models of DS, appear to suggest that RUNX1 triplication might not play a crucial role in DS-associated leukemia, but perhaps in milder phenotypes related to megakaryopoiesis and erythropoiesis." (PMID 37670378, 2023). "Although wild-type RUNX1 is necessary for the genesis of core-binding factor leukemia and rearrangements of mixed lineage leukemia AML, functional RUNX1 is also essential for hematopoietic differentiation." (PMID 37444402, 2023). "SPIB mRNA transcript levels are low in ETV6::RUNX1+ ALL relative to other leukemia subtypes, as the SPIB gene is directly activated by RUNX1 during B-cell development." (PMID 36766699, 2023). "Further study has indicated that MLF1 impairs RUNX1-ETO accumulation and reduces RUNX1-ETO-dependent leukemia cell proliferation." (PMID 36814822, 2023). "We employed MOLM14, MV4-11 and THP1 representing well characterized models of MLL-driven leukaemia, KASUMI1 as a widely used line for RUNX1-ETO fusion, and FUJIOKA and KG1A cells as models for complex karyotype leukaemias." (PMID 37996430, 2023). "ChIP–seq profiling of Stat5a, Runx1 and Runx2 confirmed the motif analysis, demonstrating cobinding of these transcription factors and BAF or MLL1 and MLL4 complexes at key pro-leukemia genes including Hoxa7 and Hoxa9." (PMID 37580596, 2023). "Runx1 can activate E2A-PBX1 expression and Runx1 itself can also be activated by E2A-PBX1 as observed in E2A-PBX1 + leukemia." (PMID 37936072, 2023). "Instead, we noticed that all leukemia cells that grow slowly in Rag2−/− mice (MLL-AF9, RUNX1-ETO9a and cSAM-2020 cells) were maintained through serial transplantations in the “non-irradiated” mice." (PMID 38129572, 2023). "Our data corroborate that RUNX1/RUNX1T1 reprograms a large transcriptional network to establish and maintain leukemia via intricate PPI interactions and kinase-driven phosphorylation events." (PMID 36980682, 2023). "Significant association was also noted between SRSF2, IDH2, and RUNX1 for leukemia-free survival, and SRSF2 and RUNX1 for myelofibrosis-free survival." (PMID 37745842, 2023). "Our data corroborate that the RUNX1/RUNX1T1 fusion reprograms a large transcriptional network to establish and maintain leukemia via intricate protein–protein interactions and kinase-driven phosphorylation events." (PMID 36980682, 2023). "Two Early-Pro cases, Ph28-D and Ph50-D, harbored concurrent deletions of EBF1, PAX5, RUNX1 and CDKN2A/B and clustered between Early-Pro and Late-Pro leukemias in PCA." (PMID 37337105, 2023). "RUNX1 inhibits proliferation and induces apoptosis via KLF4-mediated transactivation of P57 in leukemia cells." (PMID 38057816, 2023). "In pre-leukemia, this results in ETV6-RUNX1 antagonization of cell cycle regulation by RUNX1 as evidenced by mass cytometry analysis of B-lineage cells derived from ETV6-RUNX1 knock-in human pluripotent stem cells." (PMID 36411286, 2022). "Kasumi‐1 harbors oncogenic fusion of RUNX1‐ETO, which is one of the most common genetic alterations in leukemia and suppresses the expression of Cathepsin G and elastase in the lysosomes." (PMID 34407310, 2022).